HAPSTR1 (HUWE1 associated protein modifying stress responses)
Description:
Acts as a central player within a network of stress response pathways promoting cellular adaptability. The E3 ligase HUWE1 assists HAPSTR1 in controlling stress signaling and in turn, HUWE1 feeds back to promote the degradation of HAPSTR1. HAPSTR1 represents a central coordination mechanism for stress response programs.
Synonyms: C16orf72; TAPR1; FLJ41272; PRO0149
Tractability: PROTAC: UniProt records ubiquitination sites on it; ubiquitination databases record sites on it.
Gene: Protein-coding gene on chromosome 16 (9,091,610 to 9,121,635, forward strand). Ensembl gene ENSG00000182831.
Subcellular location: Nucleus; Cytoplasm
Subcellular location (Human Protein Atlas): Nucleoplasm; Vesicles
Gene Ontology:
Molecular function: protein binding; ubiquitin protein ligase binding
Biological process: regulation of cellular response to stress
Cellular component: cytoplasm; nucleus
Genetic constraint (gnomAD): Loss-of-function variants: 7 observed, 28.31 expected, observed/expected ratio (o/e) 0.25, 90% interval 0.14 to 0.46. The synonymous counts are far from expectation, so gnomAD's model fits this gene poorly and the ratio says little. Missense variants: 283 observed, 339.46 expected, observed/expected ratio (o/e) 0.83, 90% interval 0.76 to 0.92. Synonymous variants: 203 observed, 137.95 expected, observed/expected ratio (o/e) 1.47, 90% interval 1.31 to 1.65.
Homologues: Orthologues: chimpanzee HAPSTR1 (100% identical), dog HAPSTR1 (100% identical), macaque HAPSTR1 (100% identical), pig HAPSTR1 (100% identical), mouse Hapstr1 (99% identical), rat Hapstr1 (99% identical), tropical clawed frog hapstr1 (90% identical), guinea pig HAPSTR1 (81% identical), zebrafish hapstr1a (81% identical), rabbit HAPSTR1 (76% identical), Drosophila melanogaster CG4768 (32% identical), Caenorhabditis elegans haps-1 (23% identical). Paralogues in human: HAPSTR2 (68% identical).
Diseases named in the same sentence as HAPSTR1 in open-access papers:
HAPSTR1 is named in the same sentence as 13 diseases in open-access papers, as found by Europe PMC text mining. Sharing a sentence is not in itself a finding about the gene and the disease. The quoted sentences say what the papers report.
breast carcinoma (2 papers, 2023 to 2024). "By generating autochthonous breast cancer mouse models, we could show that overexpression of C16orf72/HAPSTR1 or USP7 independently accelerates Pik3caH1047R-driven mammary tumor formation." (PMID 38580884, 2024). "This led us to ask whether overexpression of C16orf72/HAPSTR1 can decrease the latency of Pik3caH1047R-driven mammary tumors." (PMID 38580884, 2024).
ovarian carcinoma (2 papers, 2024). A malignant neoplasm originating from the surface ovarian epithelium. "An immunohistochemistry assay showed that HAPSTR1 was overexpressed in ovarian cancer tissues and was significantly associated with the FIGO stage and clinical outcome." (PMID 38643468, 2024). "Due to KEGG analysis results showing that the interacting proteins of HAPSTR1 are associated with the ubiquitin-mediated proteolysis pathway, we searched for enzymes reported to play a role in ovarian cancer and are related to LRPPRC and the ubiquitin-proteasome pathway in our IP-MS results." (PMID 38643468, 2024). "However, the biological function and underlying molecular mechanisms of HAPSTR1 in ovarian cancer progression remain unclear." (PMID 38643468, 2024). "Our study is the first detailed and comprehensive analysis of HAPSTR1 in cancer progression and offers an experimental basis for the clinical treatment of ovarian carcinoma." (PMID 38643468, 2024). "Herein, we aimed to measure HAPSTR1 expression in ovarian cancer specimens and examine its correlations with clinical features and key functional interactions with other genes and proteins." (PMID 38643468, 2024).
lung carcinoma (1 paper, 2023). "To further test whether HAPSTR2 functionally buffers HAPSTR1 loss, we investigated neural-like lung cancer cells, H661, which natively express both HAPSTR1 and HAPSTR2." (PMID 36631436, 2023).
tumor (5 papers, 2023 to 2024). "We also showed that LRPPRC enhanced proliferation, invasion, and migration in OV cells, whereas LRPPRC overexpression rescued the tumor inhibitory effect caused by HAPSTR1 loss-of-function." (PMID 38643468, 2024). "The data showed that the hosts of sh-HAPSTR1 cells had smaller tumor volumes and weights than did mice in the shNC group." (PMID 38643468, 2024). "Tumor HAPSTR2 was typically low relative to HAPSTR1, but a notable subset of tumors expressed comparable amounts of both paralogs." (PMID 36631436, 2023). "Furthermore, silencing HAPSTR1 inhibited tumor growth, invasion and migration in a mouse and in vitro model." (PMID 38643468, 2024). "We also investigated the role of HAPSTR1 in the OV tumor immune environment." (PMID 38643468, 2024). "However, the direct implication of the role of C16orf72/HAPSTR1 amplification in tumor development is complicated by the fact that the USP7 gene is located adjacent to the C16orf72/HAPSTR1 locus, resulting in concurrent amplification of USP7 and C16orf72/HAPSTR1." (PMID 38580884, 2024).
cancer (4 papers, 2021 to 2024). A tumor composed of atypical neoplastic, often pleomorphic cells that invade other tissues. "The USP7 gene lies directly adjacent to C16orf72/HAPSTR1 and both genes are commonly co-amplified in up to 7.6% of cancers as well as being co-gained in up to 53% of cases (p < 0.001)." (PMID 38580884, 2024). "Residual expression of HAPSTR2 in some neural or germline cancers (and de novo expression in neural-like subsets of other cancers) also underscores a need to consider paralog effects in future studies of HAPSTR1 in cancer." (PMID 36631436, 2023). "HAPSTR2, expressed primarily in neural and germline tissues and a subset of cancers, retains established biochemical features of HAPSTR1 to achieve two functions." (PMID 36631436, 2023). "HAPSTR1 stimulates the proliferation and metastasis of some cancer cell lines." (PMID 38643468, 2024). "Given the apparent importance of HAPSTR1 in cancer, we also investigated HAPSTR2 expression in tumors and cancer cell lines." (PMID 36631436, 2023).
HAPSTR1 also shares sentences with these, for which no sentence is quoted: infection (15 papers); autism spectrum disorder (2); neurodegenerative disease (2); autism (1); fungal infection (1); Fusarium infection (1); schizophrenia (1); uterine sarcomas (1).